CD38 (CD38 molecule)
Diseases named in the same sentence as CD38 in open-access papers (continued):
Sharing a sentence is not in itself a finding about the gene and the disease.
tumor (continued). "Moreover, high expression of CD38 in MDSCs has been associated with a higher immunosuppressive capacity that results in a greater ability to suppress activated T cells and promote tumor growth in comparison with CD38low MDSCs." (PMID 41010517, 2025). "Among other factors, response to daratumumab is associated with CD38 levels on tumor cells." (PMID 38731936, 2024). "We also observed an elevated number of CD3−CD56+CD38+ NK-cells in blood, which may render these cells more susceptible (i.e., as an off-tumour target) to daratumumab itself." (PMID 39411424, 2024). "When the results of percentages of CD38-expressing cells were plotted individually, a higher proportion of CLL patients with mutated SF3B1 had >30% CD38-positive tumor cells compared with those patients with wild-type SF3B1 (median CD38 (%): 5 vs. 32; Mann–Whitney U test p = 0.0087)." (PMID 37511096, 2023). "The association could be attributed to CD38+ TAMs exhibiting the pro-inflammatory M1 phenotype, contributing to anti-tumor immune activity." (PMID 37377962, 2023). "In addition, both KCs and BMDMs responded to BG with an increase in CD38 expression, a marker associated with an anti-tumor phenotype." (PMID 37816712, 2023). "The aberrant expression of CD38 in a range of tumor types is linked to carcinogenesis." (PMID 38006053, 2023). "Furthermore, in the present study, we demonstrated a prognostic effect of CD38-positive, tumor-infiltrating plasma cells, where a higher expression of CD38 was associated with a longer MFS." (PMID 37894900, 2023). "Moreover, the metabolic pathways of adenosine and NAD+ are tightly linked through CD38, an ectoenzyme present on the surface of tumor and immune cells, which depletes NAD+ levels, which ultimately results in adenosine formation." (PMID 37842241, 2023). "This study demonstrated that an appropriate vaccination strategy combining neoantigen peptide-pulsed DC with anti-CD38 antibody can render an ICT-resistant “cold” tumor susceptible to immune rejection via a mechanism involving neutralization of regulatory T cells." (PMID 34771674, 2021). "We assessed tumor cell characteristics associated with immune suppression (PD-L1, CD47, and HVEM) or known tumor features associated with response/resistance to daratumumab treatment (expression levels of CD38 and the complement inhibitory proteins CD55 and CD59)." (PMID 34070044, 2021). "Alternatively, since the T1 and T2 naive subsets were both CD38+, daratumumab could have caused “on-target off-tumor” depletion of these subsets." (PMID 33649314, 2021). "Together, these findings highlight the important favorable prognostic implication of high 12CK-High scores in surgically treated MIBC patients and corroborates findings by other groups on the important prognostic implications of tumor-associated CD38+ plasma cells and TLS in bladder cancer." (PMID 34267760, 2021). "However, in the subgroup analysis, increased PD1+ and CD38+ CD8+ T cells were statistically significantly associated with tumor size (p = 0.004 and p = 0.036, respectively)." (PMID 33747957, 2021). "Unfortunately, CD38 is not only highly expressed on myeloma cells but also expressed at an intermediate level on hematopoietic cells, creating a real risk for on-target, off-tumor toxicity." (PMID 31379824, 2019). "Next we asked whether the effect of loss of CD38 on occurrence of brain melanoma metastasis can be attributed to inhibition of expansion/colonization of tumor cells that have invaded the brain parenchyma." (PMID 30159123, 2018). "Thus, the inhibitory effect of loss of CD38 on thickness of the peritumoral capsule, amount of CAFs and density of blood vessels is already evident early in tumor outgrowth and this effect is tumor size-independent." (PMID 30159123, 2018).
tumor (continued). "CD38 is abundantly expressed on regulatory T cells (Tregs), regulatory B cells (Bregs), myeloid-derived suppressor cells (MDSCs), tumor-associated macrophages (TAMs), and tumor-associated neutrophils (TANs), where it enhances survival, metabolic fitness, and suppressive activity." (PMID 41710886, 2026). "Notably, we observed an increase in the frequency of CD3−CD56+CD38+ NK-cells, which might render NK-cells more susceptible to daratumumab-mediated fratricide – a potentially deleterious off-tumour effect of daratumumab." (PMID 39411424, 2024). "Thus, the characterization of CD8+ T cells either isolated from the tumor site or chronically stimulated in vitro convincingly shows that expression of CD38 on Tex cells is primarily associated with the terminally differentiated subset that fails to respond to anti-PD1 therapy." (PMID 38451948, 2024). "Additionally, we could show a significant correlation between the CD38 expression and the proliferation index Ki67: a higher number of CD38-positive, tumor-infiltrating plasma cells was associated with a higher percentage of Ki67-positive tumor cells." (PMID 37894900, 2023). "Similarly, the CD133 stem cell marker, which has been reported to characterize CSCs and to be associated with a poor prognosis in different tumor types, and CD38 are also repressed by RMST, thus confirming once again its involvement in the modulation of the stem phenotype." (PMID 37393309, 2023). "Therefore, targeting CD38 poses a risk for on-target/off-tumor toxicity and could hamper an ongoing immune response during infection." (PMID 35199207, 2022). "In addition, the cADPR might also be produced by CD38 expressed on the surface of immune cells such as tumor-associated macrophages (TAMs) to promote the survival of tumor cells." (PMID 34226519, 2021). "However, previous studies have established that HCC resistance to PD-1/PD-L1 antibodies could be caused by CD38 upregulation on tumor cells." (PMID 31861847, 2019). "In conclusion, an increased understanding of host- and tumor-related features that underlie differential therapeutic efficacy and contribute to resistance toward CD38 antibodies, may lead to further optimization and individualization of treatment and a better outcome for MM patients." (PMID 30294326, 2018). "It is likely that other tumor-related factors, such as mutations in oncogenes and tumor suppressor genes, and activation status of signaling pathways also contribute to the variability in response to therapy with CD38 antibodies, but this requires further investigation." (PMID 30294326, 2018). "Through single-cell sequencing and flow cytometry, we demonstrated that patients with a better tumor response had an increased ratio of HLA-DR+CD38+CD8+ T cells in the blood after LEN-TAP conversion therapy." (PMID 41565617, 2026). "CD38 + NK cells from tumor patients can stimulate CD4 + T cells to differentiate into Tregs and macrophages to polarize into M2 type, which constitutes an immune microenvironment conducive to the growth of tumor cells." (PMID 41530841, 2026). "The patient was started on systemic anti-CD38 based therapy, which led to a rapid and substantial reduction in tumour burden." (PMID 41728229, 2026). "Daratumumab is a human IgGκ monoclonal antibody targeting CD38 with direct on-tumor and immunomodulatory mechanisms of action." (PMID 40335949, 2025). "In vivo experiments showed that mice treated with CD38/LMP1 TanCAR-T cells had smaller tumor burdens than those treated with single-target CAR-T cells, highlighting the potential of TanCAR-T cell therapy for NKTCL." (PMID 40092990, 2025). "Future research should aim to clarify the specific mode of interaction between programmed death‐ligand 1 and CD38 and their functional differences in different tumor types." (PMID 40677211, 2025). "On immunochemistry examination, the tumor cells expressed strong immunoreactivity with CD38 and CD138." (PMID 40870451, 2025).
tumor (continued). "Significantly, SAg-exposure enhanced inflammatory activation of CLL tumour cells, which acquired CD38, CD40, CD86, while downregulating CD27 (p≤0.005), even in cultures from ibrutinib-treated CLL patients." (PMID 40207214, 2025). "Having demonstrated immune-directed impacts of treatment with hCD38-mAtt in a tumor model expressing a human CD38 target, additional in vivo studies were performed using a fully murine surrogate AttenukineTM, namely mCD38-mAtt." (PMID 40315226, 2025). "This confirms the enhanced cytotoxicity of CD38‐EVs‐Dox against tumour cells, aligning with the observed differences in cellular uptake between CD38‐EVs and EVs." (PMID 40317915, 2025). "In this context, tumour infiltrating senescent T lymphocytes can affect B-cell (CD19+/CD20+) activation and their subsequent differentiation into CD27+/CD38+ cells, ultimately leading to a deficiency in antibody production and inefficient adaptive responses." (PMID 41372921, 2025). "Previous evidence from MM has shown decreases in CD38 expression on MM cells post αCD38 antibody exposure and combination drug treatment methods have been employed to help combat this method of tumor cell escape." (PMID 40057636, 2025). "Although, CD38 expression is commonly increased in MM, it is present as a tumor suppressor in HNSCC." (PMID 40173324, 2025). "CD38 has emerged as a promising therapeutic target in solid tumors due to its role in modulating the tumor microenvironment, which enables dual mechanisms of action involving direct tumor targeting and immune modulation." (PMID 41445795, 2025). "Our results demonstrate that an anti-human CD38 AttenukineTM inhibits tumor growth through direct anti-proliferative effects of IFNα on CD38 + tumor cells as well as by indirectly modulating the anti-tumor immune response." (PMID 40315226, 2025). "By regulating NAD+ levels and mitochondrial activity, CD38 ensures the stability and suppressive capacity of Tregs, which, in turn, supports tumor growth." (PMID 40117361, 2025). "In this study, we sought to delineate the effects of a CD38-targeted attenuated IFNα immunocytokine (CD38-AttenukineTM) on tumor cells and/or immune cells, through leveraging different immunocompromised and immunocompetent mouse models." (PMID 40315226, 2025). "Much due to its decade-long history as a gold-standard surface marker to detect MM cells in the bone-marrow and in peripheral blood, Syndecan-1/CD138 is an undiscussed prognostic factor in such tumour entity, when considered alone or in combination with CD38." (PMID 39980017, 2025). "Collectively, these findings indicate that CD38‐EVsMNs can efficiently and site‐specifically target tumour cells in mice while significantly limiting their distribution in the spleen and lungs." (PMID 40317915, 2025). "Tumor cells of patients with PBL are often positive for CD38; therefore, CD38 antibody is a reasonable treatment option." (PMID 41235228, 2025). "In such settings, the potential anti-tumor benefit of a CD38-targeted AttenukineTM would rely on its immune-directed effects alone." (PMID 40315226, 2025). "This indicates the superior antitumour efficacy of CD38‐EVs‐DoxMNs, corroborating the in vivo distribution and targeted delivery capabilities of CD38‐EVsMNs at tumour sites." (PMID 40317915, 2025). "In 2011, the Svachova team firstly detected nestin in mature CD138+/CD38+ plasma cell (PC) of MM patients, confirming that nestin is a tumor specific marker of CD138+/CD38+ PC in MM patients." (PMID 40799240, 2025). "The synergistic effect of these induced NK cells and a monoclonal antibody against CD38, daratumumab, has achieved to a 99% tumor reduction." (PMID 40110110, 2025). "The antitumor responses in CD38 tumor cells were attributed to both the direct antiproliferative effects of IFNα and the indirect activation of innate immune cells, including M1 macrophages and natural killer (NK) cells." (PMID 41445795, 2025).
tumor (continued). "Quantitative analysis of the percentage of CD45+ tumor cells expressing CD38 in each condition revealed a highly significant decrease in the cells treated with αCD38 antibody (p < 0.0001 by an unpaired t test)." (PMID 40057636, 2025). "Differential expression analysis also depicted altered functional capacity of T cells, with up‐regulated expression of Ki‐67 and CD38 in CD8+ Tem cells from tumours with TLS, demonstrating a higher proliferative and activated status." (PMID 39934971, 2025). "Anti-CD38 single-domain antibodies (sdAbs) labeled with 177Lu demonstrated high tumor uptake in CD38+ MM xenografts, suggesting their potential in targeted therapy." (PMID 40227793, 2025). "To elucidate the functional relevance of CD38 in intratumoral Tregs, we first examined their abundance at the tumor site." (PMID 40117361, 2025). "For instance, combining BCMA- or CD19-targeted CARs with CD38-directed CCRs has been reported to improve tumor cell killing both in vitro and in vivo, even in the context of low antigen density." (PMID 40181405, 2025). "The implantation of MDSCs crosslinked with anti-CD38 antibodies has been shown to significantly inhibit tumor growth." (PMID 40382743, 2025). "The combination of two BARs targeting different epitopes on CD38 dramatically enhanced the CDC against tumor cell lines in vitro and primary MM cells ex vivo." (PMID 41254160, 2025). "Given its central role in MDSCs metabolism and immune suppression, CD38 represents a promising therapeutic target for reprogramming the tumor microenvironment and restoring antitumor immunity." (PMID 40361394, 2025). "Pharmacological inhibition of CD38 in tumor-bearing mice resulted in a significant reduction of intratumoral Tregs, an improved Teff-to-Tregs ratio, and delayed tumor growth." (PMID 40117361, 2025). "In both in vitro and in vivo studies, NKTR-255-expanded NK cells enhanced anti-tumor cytotoxicity, suppressed tumor growth, and, when combined with the anti-CD38 antibody daratumumab, effectively inhibited multiple myeloma cells." (PMID 40852706, 2025). "The data indicated that both CD38 inhibition and anti‐PD‐1 therapy significantly inhibited tumor growth compared with that in the vehicle + IgG group, with the combination therapy exhibiting the most pronounced therapeutic benefits." (PMID 40677211, 2025). "CD38, linked to growth arrest through apoptotic pathways, and AURKA are targeted by alisertib to inhibit AR-mediated tumor growth." (PMID 40656519, 2025). "The CD38 molecule was the first target on tumor cells that was widely used in the treatment of newly diagnosed and relapsed/refractory disease thanks to the anti-CD38 monoclonal antibodies daratumumab and isatuximab." (PMID 39857790, 2025). "Taken together with the fact that TNB-738 treatment preserved the GvT response, these results indicate that inhibition of the CD38 hydrolase activity on T cells reduces local inflammation of organs while maintaining tumor infiltration and lysis by T cells." (PMID 41159029, 2025). "FCM was employed to assess the uptake of EVs and CD38‐EVs by these cells, with a comparative analysis of uptake rates between tumour and non‐tumour cells." (PMID 40317915, 2025). "Our study suggests that minimising non‐specific CD38‐EVs accumulation in the lungs and spleen is critical for better‐targeting delivery of them to tumour sites." (PMID 40317915, 2025). "Recent studies have demonstrated that ZDHHC9 mediates the S‐palmitoylation of GLUT1 and CD38, thereby stabilizing their membrane clustering with implications for tumor progression." (PMID 40828036, 2025). "CD38 + MDSCs exhibit an immature state of differentiation and possess a greater capacity to inhibit intra-tumor T-cell activity, thereby promoting tumor progression." (PMID 40382743, 2025). "To assess this, we investigated the co-expression of exhaustion markers PD-1 and CD38 on CD8+ T cell subsets from tumour tissues and matched ALI-PDOs." (PMID 41514641, 2025).
tumor (continued). "Taken together, our findings indicate that 4KO-LLT1 CAR-T cells exhibit effective and specific cytotoxicity against CD38+ tumor cells, with HLA knockdown promoting CAR-T cell proliferation and LLT1 overexpression enhancing their cytotoxicity." (PMID 39856752, 2025). "At 42 days (21 days post‐final treatment), the tumour volume in the CD38‐EVs‐DoxMNs group was markedly reduced compared to the EVs‐Doxi.v and CD38‐EVs‐Doxi.v groups." (PMID 40317915, 2025). "Highly purified LSC fraction (CD34+ CD38−) from patient-derived AML xenografts has demonstrated the ability to entirely reconstitute AML tumor heterogeneity and disease in mouse models." (PMID 41310898, 2025). "Transferring Spp1hi-TAMs significantly increased the frequency of exhausted (CD38+PD-1+) CD8+ T cells within ICI-treated tumours compared with control ICI-treated tumours." (PMID 39633050, 2025). "CD38‐EVs‐DoxMNs showed superior inhibition of tumour growth and favourable biocompatibility compared to non‐targeted EVs‐DoxMNs and CD38‐EVs‐Doxi.v." (PMID 40317915, 2025). "Inhibition of CD38 has been reported to alleviate tumor-induced immunosuppression by reducing adenosine production." (PMID 41417784, 2025). "In our study, we identified a subset of CTCL cells resistant to CD38 antibody treatment in mice, investigating its impact on post-treatment tumor growth." (PMID 40057636, 2025). "CD38‐EVs encapsulated within MNs effectively enhanced tumour cell targeting compared to standard EVs in MNs and intravenously administered CD38‐EVs, with reduced lung and spleen distribution." (PMID 40317915, 2025). "Levels of CD38 were also analyzed in tumor biopsies, via immunohistochemistry, and showed an average of ~50% positivity for CD38 staining." (PMID 41445795, 2025). "Histopathology was re-examined, and immunohistochemical analysis revealed that the tumor cells were plasmablastic and strongly positive for both CD38 and CD138." (PMID 40160869, 2025). "In immunocompromised, CD38-expressing tumor model settings, robust anti-tumor activity of hCD38-hAtt was demonstrated." (PMID 40315226, 2025). "Nonetheless, while our findings indicated the effectiveness of CD38-directed antibody therapy in eliminating tumor cells in vivo, the residual cells that persisted and evaded treatment showed a decline in CD38 expression on their surfaces." (PMID 40057636, 2025). "CD38, a multifunctional ectoenzyme and signaling protein, is involved in immune regulation, metabolic control, and tumor progression." (PMID 39996780, 2025). "A detailed analysis of paired tumor biopsies from 11 patients revealed two subgroups defined by differences in CD38 upregulation following modakafusp alfa treatment, which was accompanied by differential intratumoral pharmacodynamic changes." (PMID 41445795, 2025). "We designed CD38‐EVs for targeting tumour cells in mice via i.v injection and assessed their biodistribution in normal and tumour mouse models." (PMID 40317915, 2025). "Recent research postulated that enhancement of extracellular ADO in tumors expressing CD38 mediates not only immunosuppressive effects but also a tumor escape mechanism by increasing PD-1 expression on CD8 + cytotoxic T cells." (PMID 39805878, 2025). "As for activation markers, the expression of CD38 was increased in all T cell subtypes in the tumour sample, while HLA‐DR and CD27 were also up‐regulated in numerous T cell subsets." (PMID 39934971, 2025). "As has been previously demonstrated in the context of MM, it has been shown that various pharmacologic agents can be combined with αCD38 antibody to augment its efficacy by increasing CD38 expression on target tumor cells." (PMID 40057636, 2025). "It is also known that CD38 expression on tumor plasma cells recovers soon after the stopping treatment with anti-CD38 antibodies." (PMID 39857790, 2025).